NPAS4 (neuronal PAS domain protein 4)
Diseases named in the same sentence as NPAS4 in open-access papers (continued):
Sharing a sentence is not in itself a finding about the gene and the disease.
tumor (1 paper, 2018). "Further analysis revealed that NPAS4 protein levels were also significantly downregulated in the hippocampi of tumor-bearing mice." (PMID 29556248, 2018). "We also noted that tumor growth led to downregulation of NPAS4, BDNF, and several other neurotrophic factors." (PMID 29556248, 2018). "The observed concomitant downregulation of AKT1, ERK1/2, NPAS4, BDNF, and other NPAS4 targets strongly suggests the importance of these pathways in tumor brain, as it manifests in the hippocampus." (PMID 29556248, 2018). "TNBC and PR+BC tumor growth also led to a significant decrease in the levels of neuronal transcription factor NPAS4, a regulator that governs the expression of brain-derived neurotrophic factor (BDNF), and several other key brain neurotrophic factors and pro-survival molecules." (PMID 29556248, 2018). "We noted a significant downregulation of Npas4 and its target genes in the hippocampal tissues of TNBC- and PR+BC tumor-bearing animals, as compared to controls." (PMID 29556248, 2018). "In-depth gene expression analysis revealed that Npas4 was one of the most downregulated genes in the hippocampi of both TNBC and PR+BC tumor-bearing animals, as compared to controls (log fold −1.74 and −1.38, respectively)." (PMID 29556248, 2018). "The current study open news avenues to further dissect the potential driving mechanisms and functional consequences of the reduced levels of AKT1, ERK1/2, NPAS4 and BDNF in tumor brain, especially within the concept of aging." (PMID 29556248, 2018). "The decreased expression of ERK1/2, NPAS4, and BDNF are also seen in neurodegenerative conditions and aging, and may constitute an important tumor brain mechanism." (PMID 29556248, 2018).
NPAS4 also shares sentences with these, for which no sentence is quoted: Seizure (2 papers); Ataxia (1); brain inflammation (1); cancer (1); cardiovascular diseases (1); CNS tumor (1); cocaine addiction (1); cognitive disorder (1); esophagus cancer (1); hemorrhage (1); hypertrophy (1); Insulin resistance (1); Intellectual disability (1); large intestine cancer (1); liver cancer (1); mental disorder (1); movement disorder (1); scrapie (1); Sepsis (1); skin cancer (1); tauopathies (1); type 2 diabetes (1); uterine leiomyosarcoma (1).